PIK3R2 (phosphoinositide-3-kinase regulatory subunit 2)
Description:
Regulatory subunit of phosphoinositide-3-kinase (PI3K), a kinase that phosphorylates PtdIns(4,5)P2 (Phosphatidylinositol 4,5-bisphosphate) to generate phosphatidylinositol 3,4,5-trisphosphate (PIP3). PIP3 plays a key role by recruiting PH domain-containing proteins to the membrane, including AKT1 and PDPK1, activating signaling cascades involved in cell growth, survival, proliferation, motility and morphology. Binds to activated (phosphorylated) protein-tyrosine kinases, through its SH2 domain, and acts as an adapter, mediating the association of the p110 catalytic unit to the plasma membrane. Indirectly regulates autophagy. Promotes nuclear translocation of XBP1 isoform 2 in a ER stress- and/or insulin-dependent manner during metabolic overloading in the liver and hence plays a role in glucose tolerance improvement (By similarity).
Synonyms: P85B; p85; p85beta; p85-BETA; MPPH; MPPH1
Tractability: Small molecule: a drug acting on it is in phase 2 or 3 trials; a high-quality ligand is known. PROTAC: UniProt records ubiquitination sites on it; ubiquitination databases record sites on it; its protein half-life has been measured; a small molecule that binds it is known.
Target class: Enzyme
Safety:
Unwanted effects reported when the protein is acted on. In parentheses: how it was acted on, where the effect was seen, and who reports it.
neutropenia (source: ClinPGx)
Gene: Protein-coding gene on chromosome 19 (18,153,160 to 18,170,541, forward strand). Ensembl gene ENSG00000105647.
Subcellular location (Human Protein Atlas): Golgi apparatus
Pathways (Reactome):
Signal Transduction: CDC42 GTPase cycle; Downstream signal transduction; Extra-nuclear estrogen signaling; G alpha (q) signalling events; IRS-mediated signalling; PI3K Cascade; PI3K/AKT activation; PI5P, PP2A and IER3 Regulate PI3K/AKT Signaling; PIP3 activates AKT signaling; RAC1 GTPase cycle; RAC2 GTPase cycle; RAC3 GTPase cycle; RAF/MAP kinase cascade; RHOA GTPase cycle; RHOB GTPase cycle; RHOD GTPase cycle; RHOF GTPase cycle; RHOJ GTPase cycle; RHOU GTPase cycle; RND1 GTPase cycle; RND2 GTPase cycle; RND3 GTPase cycle; Signaling by ALK; Signaling by LTK; Signaling by SCF-KIT; VEGFA-VEGFR2 Pathway
Immune System: CD28 dependent PI3K/Akt signaling; Co-stimulation by ICOS; DAP12 signaling; Downstream TCR signaling; Interleukin receptor SHC signaling; Interleukin-3, Interleukin-5 and GM-CSF signaling; Interleukin-7 signaling; Regulation of signaling by CBL; Role of LAT2/NTAL/LAB on calcium mobilization; Role of phospholipids in phagocytosis
Disease: Constitutive Signaling by Aberrant PI3K in Cancer; Signaling by ALK fusions and activated point mutants; Signaling by LTK in cancer; Signaling by PDGFRA extracellular domain mutants
and 8 more pathways
Gene Ontology:
Molecular function: phosphotyrosine residue binding; protein binding; protein phosphatase binding; receptor tyrosine kinase binding; 1-phosphatidylinositol-3-kinase regulator activity; phosphatidylinositol 3-kinase regulatory subunit binding; protein heterodimerization activity
Biological process: negative regulation of MAPK cascade; phosphatidylinositol 3-kinase/protein kinase B signal transduction; regulation of autophagy; B cell differentiation; cellular response to insulin stimulus; immune response; insulin receptor signaling pathway; intracellular glucose homeostasis; positive regulation of protein import into nucleus; positive regulation of transcription by RNA polymerase II; response to endoplasmic reticulum stress; T cell differentiation; signal transduction
Cellular component: phosphatidylinositol 3-kinase complex, class IA; cytosol; nucleus; focal adhesion
Genetic constraint (gnomAD): Loss-of-function variants: 40 observed, 68.47 expected, observed/expected ratio (o/e) 0.58, 90% interval 0.45 to 0.76. The upper end of that interval is the gene's LOEUF score, 0.76, which puts it in group 3 of 6, group 1 being the genes least tolerant of losing a copy. Missense variants: 826 observed, 875.38 expected, observed/expected ratio (o/e) 0.94, 90% interval 0.89 to 1. Synonymous variants: 444 observed, 381.55 expected, observed/expected ratio (o/e) 1.16, 90% interval 1.08 to 1.26.
Gene-disease validity (ClinGen):
ClinGen rates the evidence that PIK3R2 causes each of these diseases.
overgrowth syndrome and/or cerebral malformations due to abnormalities in MTOR pathway genes (autosomal dominant): Definitive. A disease caused by mosaic gain-of-function (GoF) of several genes in the MTOR pathway (MTOR, PIK3CA, PIK3R2 and AKT3) are functionally the same despite significant phenotypic variability.
Homologues: Orthologues: chimpanzee PIK3R2 (99% identical), macaque PIK3R2 (98% identical), dog PIK3R2 (97% identical), pig PIK3R2 (96% identical), mouse Pik3r2 (89% identical), rat Pik3r2 (88% identical), guinea pig PIK3R2 (82% identical), tropical clawed frog pik3r2 (64% identical), zebrafish pik3r2 (62% identical), Drosophila melanogaster Pi3K21B (22% identical), Caenorhabditis elegans aap-1 (18% identical). Paralogues in human: PIK3R1 (59% identical), PIK3R3 (42% identical).
Diseases named in the same sentence as PIK3R2 in open-access papers:
PIK3R2 is named in the same sentence as 111 diseases in open-access papers, as found by Europe PMC text mining. Sharing a sentence is not in itself a finding about the gene and the disease. The quoted sentences say what the papers report.
breast carcinoma (24 papers, 2012 to 2025). "But PIK3R2 expression levels were found to be elevated in advanced cancer stages of colon and breast cancers and were associated with tumor progression." (PMID 35395865, 2022). "Almost two-thirds of breast cancer show decreased expression of PIK3R1, which encodes for p85α, while increased expression of PIK3R2, which encodes for p85β, is seen in 45% of breast cancers." (PMID 34769309, 2021). "Thus, a potential mode of addressing breast cancer resistance to trastuzumab is highlighted in this study mainly by the use of a microRNA to inhibit PIK3R2 and its associated pathway." (PMID 32410348, 2020). "As for miR-126, Fu and Tong found that lower miR-126 facilitated the ability of migration and invasion of trastuzumab-resistant breast cancer cells through targeting miR-126/PIK3R2 axis." (PMID 37529418, 2023). "We chose to analyze the following four TCGA datasets because PIK3CA is frequently mutated, and PIK3R2 is overexpressed in these tumor types: colorectal cancer (COAD), bladder carcinoma (BLCA), endometrial carcinoma (UCEC), and breast cancer (BRCA)." (PMID 35418124, 2022). "In one group of colon and breast cancer samples, Pik3r2 expression levels were elevated in 50% of tumors." (PMID 35468821, 2022). "For instance, in breast cancer, miR-126-5p targets the PIK3R2 mRNA and sequentially suppressed the resistance to trastuzumab in tumor cells via degenerating PIK3R2 expression." (PMID 36535956, 2022). "The results of our study on breast cancer demonstrate that this network is regulated by miR‐126 and its target PIK3R2." (PMID 32410348, 2020). "miR-126-3p is involved with the VEGF/PI3K/AKT signaling pathway and targets both VEGFA and PIK3R2, playing a role in vasculogenesis and tumor growth in human breast cancer." (PMID 27191494, 2016). "Increased expression of PIK3R2, which encodes the regulatory subunit p85β, enhances basal PI3K pathway activation and parallels tumor progression in melanoma, colon cancer and breast carcinoma." (PMID 27835880, 2016). "PIK3R2 has been shown to be functionally associated with unphosphorylated PTEN and the PTEN-associated complex in some HER2-amplified breast cancer cell lines." (PMID 22952662, 2012). "PI3K regulatory subunit PIK3R2 could also be modulated by IRF6 through the PI3K‐Akt pathway to control the pathogenesis of breast cancer." (PMID 33934391, 2021). "It was also found that miR‐126 directly targets PIK3R2 in breast cancer cells." (PMID 32410348, 2020). "For example, in breast cancer, PIK3R2 (phosphoinositide-3-kinase, regulatory subunit 2 beta) and ECT2 (epithelial cell transforming sequence 2 oncogene) have a TARGETgene rank of 37 and 272, and with a 3.31 and 4.94 fold change in gene expression of breast cancer tissues, respectively." (PMID 22952662, 2012).
melanoma (13 papers, 2013 to 2025). A malignant, usually aggressive tumor composed of atypical, neoplastic melanocytes. "The upregulation of AHR, MAP2K1, and PRKACB, alongside the downregulation of KLF5 and PIK3R2, suggests that these genes play critical roles in melanoma progression through various signaling pathways." (PMID 39835132, 2024). "PIK3R2, encoding the regulatory subunit of phosphoinositide-3-kinase (PI3K), is frequently activated in various cancers, including melanoma." (PMID 39835132, 2024). "PIK3R2 is identified to promote malignant progression of melanoma by activating the PI3K/AKT/NF - κ B pathway." (PMID 39835132, 2024). "Our analysis identified a robust prognostic model, with four AhR-related genes (MAP2K1, PRKACB, KLF5, and PIK3R2) emerging as key contributors to melanoma progression." (PMID 39835132, 2024). "PIK3R2, which encodes the p85ß regulatory subunit of PI3K (phosphatidylinositol-3-kinase), is frequently overexpressed in melanoma, breast, and squamous cell lung carcinoma, and its expression level increases during tumor progression." (PMID 35203530, 2022). "Previous studies showed that the expression of PIK3R2 increases with the advanced tumor stage in melanoma, breast, and squamous cell lung carcinoma." (PMID 35087740, 2021). "Up to date, only ADAM9, MMP7 and PIK3R2 have been validated as direct miR-126-3p&5p target genes in drug treatment-naïve melanoma cells." (PMID 31227006, 2019). "Additionally, several bioinformatics analyses based on melanoma transcriptome have indicated that PIK3R2 leads to poor prognosis and low immune cell infiltration in melanoma." (PMID 39835132, 2024). "Conversely, the downregulation of KLF5 and PIK3R2 may facilitate a more aggressive, proliferative melanoma phenotype by affecting cell differentiation and metabolism." (PMID 39835132, 2024). "PIK3R2 (p85β) would represent one of the genes controlling cell invasion in advanced melanoma." (PMID 25217619, 2014). "We have tested the consequences of depleting PIK3R2 only in lung SQCC lines; it is possible that other tumor types showing enhanced PIK3R2 expression at advances phases, such as breast and colon carcinoma or melanoma, might also benefit from a therapeutic strategy based on PIK3R2 depletion." (PMID 27835880, 2016). "These analyses aim to uncover potential therapeutic strategies for melanoma by targeting key molecules in the AHR, MAP2K1, KLF5, PRKACB, and PIK3R2 signaling pathways." (PMID 39835132, 2024). "This study presents a comprehensive analysis of AhR-related genes in melanoma, highlighting MAP2K1, PRKACB, KLF5, and PIK3R2 as key prognostic markers and potential therapeutic targets." (PMID 39835132, 2024). "This study provides an integrated approach to understanding the AhR pathway’s role in melanoma, identifying MAP2K1, PRKACB, KLF5, and PIK3R2 as critical prognostic markers and therapeutic targets." (PMID 39835132, 2024). "These analyses aim to identify therapeutic strategies for melanoma by targeting key genes (AHR, MAP2K1, KLF5, PRKACB, PIK3R2) and their regulatory RNA networks, offering potential for personalized treatments and novel biomarkers to improve clinical outcomes." (PMID 39835132, 2024). "In LN, MAPK3 (cf = 53), PIK3R1 (cf = 51), HRAS (cf = 46), PIK3R2 (cf = 45) and KRAS (cf = 44) are the top 5 cross-talk genes, and as expected most of these are already recognized melanoma markers." (PMID 26558755, 2015). "Five genes (CXCL10, TNF, PIK3CD, PIK3R2, and CXCL1) of the TNF signalling pathway and seven genes (CXCL9, GDF15, BMP7, TNFRSF15, CXCL10, TNF, and CXCL1) of the cytokine–cytokine receptor pathway were commonly upregulated in melanoma cells." (PMID 39496484, 2024).
melanoma (continued). "An examination of the expression profiles of melanoma patients from the TCGA database, compared to normal controls from the GTEx database, revealed that AHR, MAP2K1, and PRKACB were upregulated in melanoma, whereas KLF5 and PIK3R2 were downregulated." (PMID 39835132, 2024). "Our results show that, similarly to PIK3R2, NFKB1 gene expression is down-regulated by D6 in melanoma cells (FC = 0.47), but it is unclear whether this could be due to the PI3K/Akt signalling repression." (PMID 23642048, 2013).
lung carcinoma (11 papers, 2013 to 2025). "DNAm modifications of MAPK10, PLCG1, PLCβ3 and PIK3R2 genes were consistently linked between the lung and blood samples, suggesting their pivotal role in radon-induced lung cancer." (PMID 40725119, 2025). "In lung cancer, PIK3R2 mutation may lead to the anomalous activation of the PI3K signaling pathway and fostered tumor progression and development." (PMID 40725119, 2025). "The DNAm episignatures of MAPK10, PLCG1, PLCβ3 and PIK3R2 have a significant influence on radon-induced lung cancer." (PMID 40725119, 2025). "Co-targeting miR-126-3p and miR-221-3p inhibits lung cancer development and metastasis by suppressing PIK3R2 and PTEN." (PMID 38460046, 2024). "Systemic delivery of a combination of miR‐126‐3p mimic and miR‐221‐3p inhibitor encapsulated in lipid nanoparticles reduced lung cancer patient‐derived xenograft growth through blockade of the PIK3R2–AKT pathway." (PMID 34107168, 2021). "It has been shown that up-regulation of miR-30a-5p in lung cancer cells reduces expression of the PI3K regulatory subunit PIK3R2 to induce cell apoptosis and inhibit cell invasion and migration." (PMID 29959359, 2018). "Accordingly, it is hypothesized that PIK3R2 3′-UTR hypomethylation may promote the development of lung cancer by enhancing mRNA stability and translation efficiency." (PMID 40725119, 2025). "They found that concomitant miR-126-3p activation and miR-221-3p inhibition reduced lung cancer cell viability by inhibiting AKT, PIK3R2 and PTEN (Phosphatase And Tensin Homolog) signaling pathways." (PMID 38469304, 2024). "We find that lung squamous cell carcinoma (SQCC), which accounts for ~20% of lung cancer, exhibits increased expression of the PI3K subunit PIK3R2, which is at low expression levels in normal tissues." (PMID 27835880, 2016). "In addition, radon exposure promoted lung cancer development in the genetic engineering mouse model (GEMM), accompanied by decreased MAPK10 and increased PLCG1, PLCβ3, and PIK3R2 with mRNA and protein levels." (PMID 40725119, 2025). "Although statistical analysis displayed that the expression differences of PIK3R1 and PIK3R2 in lung cancer, stomach cancer, or other cancers were not statistically significant, which may be due to the small sample size, their abnormal expression in cancer was distinct." (PMID 35395865, 2022).
ovarian carcinoma (11 papers, 2011 to 2025). A malignant neoplasm originating from the surface ovarian epithelium. "The association of IRS4 and PIK3R2 was also decreased in FER-deficient OVCAR-5 ovarian cancer cells." (PMID 35550247, 2022). "Intriguingly, high PIK3R2 mRNA levels were significantly associated with relatively poor overall survival and progression-free survival in ovarian cancer patients." (PMID 32385243, 2020). "Despite the absence of a significant correlation with overall survival (p = 0.16), these findings suggest potential ancestry-associated differences in PIK3R2 expression that may contribute to biological heterogeneity in ovarian carcinoma." (PMID 41294900, 2025). "Further studies with larger and racially diverse cohorts are warranted to validate these observations and clarify the role of PIK3R2 in ovarian cancer disparities." (PMID 41294900, 2025). "This included confirmed partial responses in two patients: one with endometrial adenocarcinoma harboring a PIK3R2 alteration, and one with ovarian carcinoma harboring a PIK3CA and PTEN alterations." (PMID 38643311, 2024). "FER-mediated PIK3R2 recruitment by insulin receptor substrate 4 (IRS4) is crucial to ovarian cancer cell proliferation in vitro and tumorigenesis in vivo." (PMID 35550247, 2022). "Meanwhile, we also observed a higher proteomic expression level of PIK3R2 in liver cancer and ovarian cancer compared to normal tissues." (PMID 35395865, 2022). "Together, our findings provide a rationale for pharmacological blockade of the AXL signaling axis in PIK3R2-amplified ovarian cancer." (PMID 32385243, 2020). "Collectively, genetic ablation or pharmacological inhibition of tyrosine kinase FER in ovarian cancer cells leads to decreased global tyrosine phosphorylation and PIK3R2 recruitment of IRS4, which is consistent with our ectopic overexpression studies in HEK293FT cells." (PMID 35550247, 2022). "While ectopic overexpression of FER dramatically increased tyrosine phosphorylation and PIK3R2 recruitment of IRS4, CRISPR-Cas9 directed KO or pharmacological inhibition of the endogenous kinase in ovarian cancer cells remarkably reduced tyrosine phosphorylation and PIK3R2 recruitment of IRS4." (PMID 35550247, 2022). "PIK3R2, the regulatory subunit p85β of the PI3K complex, is increasingly recognized as a key mediator of PI3K/AKT signaling in ovarian cancer." (PMID 41294900, 2025). "The regulatory subunit p85β of the PI3K complex, called PIK3R2, is increasingly recognized as a key mediator of PI3K/AKT signaling in ovarian cancer." (PMID 41294900, 2025). "Two patients had a confirmed partial response to treatment: one with endometrial adenocarcinoma and phosphoinositide-3-kinase regulatory subunit 2 (PIK3R2) alteration, and one with ovarian carcinoma and PIK3CA and PTEN alterations." (PMID 38643311, 2024). "Fer promotes also the deregulated proliferation of ovarian cancer cells by phosphorylating the insulin receptor substrate four (IRS4), thereby enabling it to recruit the PIK3R2/p85β-subunit of PI3K, and to activate the PI3K-AKT pathway." (PMID 36982326, 2023). "Using a proximity-based tagging system in ovarian carcinoma-derived OVCAR-5 cells, we determined that FER-mediated phosphorylation of Tyr779 enables IRS4 to recruit PIK3R2/p85β, the regulatory subunit of PI3K, and activate the PI3K-AKT pathway." (PMID 35550247, 2022). "As the key regulatory subunit of PI3K kinase, recruitment of PIK3R2/p85β onto IRS4 is required for PI3K-AKT signaling pathway activation and tumorigenesis in ovarian cancer." (PMID 35550247, 2022). "FER-mediated phosphorylation of Tyr779 on IRS4 enhances recruitment of PIK3R2/p85β, the regulatory subunit of PI3K, and promotes PI3K-AKT signaling pathway, which eventually leading to cell proliferation and tumorigenesis in ovarian cancer." (PMID 35550247, 2022). "Together, we deduced that MED12, LRP2, PIK3R2, CCNE1, and LRP1B might be potential biomarkers for immunotherapy of ovarian cancer." (PMID 33432021, 2021).
ovarian carcinoma (continued). "Here we report that p85β signals through its upstream kinase AXL, which in turn activates p110 to induce PDK1/SGK3 signaling, establishing the mechanistic basis for targeting AXL in PIK3R2-amplified ovarian cancer." (PMID 32385243, 2020). "In our study, an expression profiling from 80 ovarian carcinomas unveiled the regulatory subunit PIK3R2 as a negative prognosis factor for ovarian cancer." (PMID 21967738, 2011).